CAVIN2 (caveolae associated protein 2)
Description:
Plays an important role in caveolar biogenesis and morphology. Regulates caveolae morphology by inducing membrane curvature within caveolae. Plays a role in caveola formation in a tissue-specific manner. Required for the formation of caveolae in the lung and fat endothelia but not in the heart endothelia. Negatively regulates the size or stability of CAVIN complexes in the lung endothelial cells. May play a role in targeting PRKCA to caveolae (By similarity).
Synonyms: SDPR; SDR; PS-p68; cavin-2
Tractability: Antibody: its Gene Ontology location is reachable by antibodies, with high confidence; the Human Protein Atlas places it where antibodies can reach. PROTAC: ubiquitination databases record sites on it.
Gene: Protein-coding gene on chromosome 2 (191,834,305 to 191,847,211, reverse strand). Ensembl gene ENSG00000168497.
Subcellular location: Cytoplasm, cytosol; Membrane, caveola
Subcellular location (Human Protein Atlas): Plasma membrane; Cytosol
Gene Ontology:
Molecular function: phosphatidylserine binding; protein binding; phospholipid binding; protein kinase C binding
Biological process: plasma membrane tubulation
Cellular component: caveola; cytoplasm; cytosol; membrane raft; plasma membrane
Genetic constraint (gnomAD): Loss-of-function variants: 14 observed, 13.63 expected, observed/expected ratio (o/e) 1.03, 90% interval 0.68 to 1.59. The upper end of that interval is the gene's LOEUF score, 1.59, which puts it in group 6 of 6, group 1 being the genes least tolerant of losing a copy. Missense variants: 549 observed, 576.78 expected, observed/expected ratio (o/e) 0.95, 90% interval 0.89 to 1.02. Synonymous variants: 237 observed, 239.42 expected, observed/expected ratio (o/e) 0.99, 90% interval 0.89 to 1.1.
Homologues: Orthologues: chimpanzee CAVIN2 (99% identical), macaque CAVIN2 (96% identical), pig CAVIN2 (87% identical), rabbit CAVIN2 (87% identical), mouse Cavin2 (83% identical), rat Cavin2 (82% identical), guinea pig CAVIN2 (76% identical), dog CAVIN2 (62% identical), tropical clawed frog cavin2 (53% identical), zebrafish cavin2b (52% identical), zebrafish cavin2a (38% identical). Paralogues in human: CAVIN1 (31% identical), CAVIN4 (25% identical), CAVIN3 (24% identical).
Diseases named in the same sentence as CAVIN2 in open-access papers:
CAVIN2 is named in the same sentence as 46 diseases in open-access papers, as found by Europe PMC text mining. Sharing a sentence is not in itself a finding about the gene and the disease. The quoted sentences say what the papers report.
breast carcinoma (14 papers, 2015 to 2025). "Protein levels of all CAVs, CAVIN1, and CAVIN2 were associated with RFS of patients with Luminal A breast cancer, suggesting these caveolae-related genes can be potentially independent predictive factors of the prognosis of Luminal A breast cancer." (PMID 34513683, 2021). "Both CAVIN1 and CAVIN2 were significantly downregulated in breast cancer tissues and were associated with prognosis of patients." (PMID 34513683, 2021). "Furthermore, investigations on survival of patients with breast cancer indicated outstanding associations between prognosis and CAVIN2 levels, especially for the patients with estrogen receptor positive (ER+) breast cancer." (PMID 34513683, 2021). "Cavin-2 acts as a breast cancer suppressor, inhibiting breast cancer progression by blocking the transforming growth factor (TGF-β) signaling pathway." (PMID 37828916, 2023). "Our group previously found that CAVIN2/SDPR depletion can induce epithelial-mesenchymal transition in breast cancer cells by activating TGF-β signaling pathway." (PMID 37497407, 2023). "The statistical results showed that CAV1, CAV2, CAV3, CAVIN1, and CAVIN2 were significantly less expressed in breast cancer tissues than in normal ones." (PMID 34513683, 2021). "Our results elucidated that lower expression of CAV3, CAVIN1, and CAVIN2 significantly related to OS of patients with Luminal A breast cancer." (PMID 34513683, 2021). "Taken together, these results revealed a remarkable prognostic potential of CAVIN2 in breast cancer populations." (PMID 34513683, 2021). "Based on the survival results, we then implemented Gene Set Enrichment Analysis (GSEA) analysis to explore the relevant signaling pathways of CAVIN2 high expression group and low expression group of patients with breast cancer patients." (PMID 34513683, 2021). "The comprehensive analysis of cavins’ expressions and functions had provided evidences of significant roles of CAVIN1 and CAVIN2 in inhibiting breast cancer development." (PMID 34513683, 2021). "A previous study of our group has discovered that cavin-2 depletion can induce epithelial-mesenchymal transition in breast cancer cells by activating TGF-β signaling pathway." (PMID 34513683, 2021). "In conclusion, CAVIN2 achieved the highest potential of independently predicting prognosis of patients with ER+ breast cancer among all the caveolae-related genes." (PMID 34513683, 2021). "As previous studies have proved that downregulation of CAVIN2 could cause reduction in CAVIN1 and CAV1 expression, the interdependency of these 3 molecules makes CAVIN2 as a prominent therapeutic target in breast cancer treatment." (PMID 34513683, 2021). "In conclusion, our investigation indicated CAVIN2 is a potential therapeutic target for patients with ER+ breast cancer, which may relate to functions of cancer cell surface receptors and adhesion molecules." (PMID 34513683, 2021). "Downregulation of CAVIN2 in breast cancer tissues was the most significant of all caveolae-related genes, and it could assess prognostic values of patients with breast cancer in regardless of all others CAVINs." (PMID 34513683, 2021). "Our findings suggested CAVIN2 could be potential targets for breast cancer therapy." (PMID 34513683, 2021). "A strong convergence was also observed for breast cancer: all manuscript-listed genes, including SCARA5, ADAMTS5, MMP11 and CAVIN2, appeared in the outputs of SHAP or LIME." (PMID 40565055, 2025). "The results elucidated that the transcriptional levels of CAV1, CAV2, CAVIN1, CAVIN2, and CAVIN3 were significantly lower in breast cancer tissues than in normal samples." (PMID 34513683, 2021). "Results elucidated that expression levels of CAV1, CAV2, CAVIN1, CAVIN2, and CAVIN3 were significantly lower in breast cancer tissues than in normal samples, while the expression level of CAVIN2 was correlated with advanced tumor stage." (PMID 34513683, 2021).
breast carcinoma (continued). "There is a number of scientific research for each of the top 10 mRNA genes, well-documenting their significance and association with cancerogenesis: ADAMTS5, TMEM220, ARHGAP20, MICU3; or precisely with breast cancer: COL10A1, MMP11, CAVIN2 (formerly known as SDPR), PLPP3, MME, and CD300LG." (PMID 40724805, 2025). "Furthermore, the associations between protein levels and survival of patients was the most obvious in the KM curves revealing the expression of CAVIN2 and RFS of HER2 negative, progesterone receptor (PR) positive, and estrogen receptor (ER) positive breast cancer." (PMID 34513683, 2021).
gastric cancer (5 papers, 2019 to 2025). A primary or metastatic malignant neoplasm involving the stomach. "PTRF, also named CAVIN1, is an unfavorable prognosis marker for ovarian, urothelial, and colorectal cancers, whereas SDPR (known as CAVIN2) is associated with a favorable prognosis in renal cancer and a poor prognosis in stomach cancer." (PMID 37775701, 2023).
lung carcinoma (4 papers, 2021 to 2025). "In addition, CAVIN2 expression increases the sensitivity of lung cancer cells to anticancer drugs." (PMID 36067196, 2022). "In detail, according to the different types of lung cancer, CAV1, CAV2, CAVIN1 and CAVIN2 had a dramatically lower expression in lung adenocarcinoma, squamous cell lung carcinoma and large cell lung carcinoma." (PMID 37497407, 2023).
colorectal cancer (2 papers, 2020 to 2023). A primary or metastatic malignant neoplasm that affects the colon or rectum. "Cavin-2 or caveolae-associated protein (Sdpr), which we found to be upregulated in both AG.1 and 5-FU treated groups, interacts with Cavin-1 (Ptrf) and both have a role in suppressing the progression and metastasis of colorectal cancers." (PMID 32973493, 2020).
depression (2 papers, 2023 to 2025). "Furthermore, two single nucleotide polymorphisms in CAVIN 2 have previously been associated with depression." (PMID 38049858, 2023).
diabetic retinopathy (2 papers, 2017 to 2022). "High cavin-2 expression in angiogenic neovascular tufts indicates that Cavin-2 could be involved in pathogenic angiogenesis such as age-related macular degeneration and diabetic retinopathy." (PMID 28912276, 2017).
Insulin resistance (2 papers, 2020 to 2022). Increased resistance towards insulin, that is, diminished effectiveness of insulin in reducing blood glucose levels. "Our previous work identified a strong positive correlation between adipose cavin-2 expression and the HOMA-IR of obese diabetic patient, highlighting the impact of caveolae disassembly in insulin resistance development." (PMID 33324235, 2020). "Finally, we have identified a strong positive correlation between adipose cavin-2 downregulation and the HOMA-IR (homeostasis model assessment of insulin resistance) of obese diabetic patient highlighting the importance of functional plasma membrane caveolae in insulin signaling." (PMID 33324235, 2020).
COVID-19 (1 paper, 2022). A disease caused by infection with severe acute respiratory syndrome coronavirus 2. "Contrary to the trend observed in G2, in a single-cell sequencing study of 16 COVID-19 patients, megakaryocyte progenitor cells/platelets showed increased expression of CAVIN2." (PMID 35438176, 2022).
disc degeneration (1 paper, 2022). "In recent studies, caveolae associated protein 2 (Cavin-2) modified engineered extracellular vesicles were used to treat disc degeneration." (PMID 35163637, 2022).
Hepatic fibrosis (1 paper, 2021). The presence of excessive fibrous connective tissue in the liver. "Overall, CAVIN2+ Kupffer cells were the main source of TGFB1, consisting primarily of mononuclear phagocytes in the livers of the SJ group subjects and potentially playing an irreplaceable role in hepatic fibrosis of schistosomiasis." (PMID 34355810, 2021).
kidney cancer (1 paper, 2021). Primary or metastatic malignant neoplasm involving the kidney. "However, we can conclude from Oncomine results that only CAVIN2 were downregulated in most types of cancers, while the expression levels of others were significantly elevated in specific types of cancers such as kidney cancer and lymphoma." (PMID 34513683, 2021).
leukemia (1 paper, 2022). A malignant (clonal) hematologic disorder, involving hematopoietic stem cells and characterized by the presence of primitive or atypical myeloid or lymphoid cells in the bone marrow and the blood. "Interestingly, low expression of CAVIN1 and CAVIN4 is correlated with poorer outcome but low CAVIN2 expression is associated with a significantly better leukemia prognosis in leukemia." (PMID 35722492, 2022). "CAVIN2 relatively high expression was often found in myeloid leukemia and predicted a poorer prognosis, which may be regarded as potential prognostic biomarkers, diagnostic subtype indicators and therapy targets for leukemia." (PMID 35722492, 2022). "In our study, ONCOMINE and GEPIA dataset analysis revealed that the mRNA expression of Cavin family members, especially CAVIN1 and CAVIN2, was lower in human leukemia than that in normal cells, as the same as in most tumors." (PMID 35722492, 2022). "In particular, overexpressed CAVIN4 was associated with a better overall survival (OS), as we expected, but there was obviously better OS with high vs. low expression of CAVIN2 in leukemia (p = 0.017) by R-programing in our report." (PMID 35722492, 2022). "High Cavin-2 and low Cavin-4 levels predict poor survival and could be promising subtype diagnosis and prognosis biomarkers for leukemia." (PMID 35722492, 2022). "In addition, we verified the Cavin-1 and Cavin-2 protein levels by Western blotting and indicated they were also lower in leukemia cells than in normal peripheral blood mononuclear cells (PBMCs)." (PMID 35722492, 2022). "Finally, we investigated the prognostic value of CAVIN1, CAVIN2, CAVIN3, and CAVIN4 in leukemia using the R programming language to assess data from LinkedOmics." (PMID 35722492, 2022). "All in all, higher Cavin-2 may promote the resistance and progression of leukemia by regulating cell differentiation, proliferation, angiogenesis and MDR-1 or EGFR expression." (PMID 35722492, 2022). "We then used the GEPIA and BloodSpot database to validate the unexpected result and found that high CAVIN2 expression was significantly associated with poorer OS in leukemia (p is 0.037 and 0.022 individually), but the trend was not significant for CAVIN1, CAVIN3 and CAVIN4." (PMID 35722492, 2022). "However, patients with CAVIN2-overexpressing leukemia had even better survival (p = 0.017)." (PMID 35722492, 2022). "We found higher expression of CAVIN2 was certainly associated with a poorer prognosis (p is equal to 0.037 and 0.0022 individually), but the expression levels of other members have no statistical correlation with the prognosis of leukemia." (PMID 35722492, 2022). "The expression of CAVIN1 and CAVIN2 is higher in myeloid leukemia than lymphoblastic leukemia, while CAVIN4 expression is just the opposite in leukemia." (PMID 35722492, 2022). "Consistently, the mRNA level of CAVIN1 was positively correlated with CAVIN2 (R = 0.47, p < 0.05) but not significantly correlated with any other Cavin family members in leukemia." (PMID 35722492, 2022). "We might hypothesize that the Cavin family, especially CAVIN2 and CAVIN4, could be potential markers of the clinicopathological parameters of patients with different types of leukemia." (PMID 35722492, 2022).
lymphoblastic leukemia (1 paper, 2022). "Cavin-1 and Cavin-2 are often more expressed in myeloid leukemia than lymphoblastic leukemia, but Cavin-4 has the opposite pattern." (PMID 35722492, 2022).
lymphocytic leukemias (1 paper, 2022). "We found that the expression level of both CAVIN1 and CAVIN2 in myeloid leukemia is higher than that in lymphocytic leukemia, while the expression of CAVIN4 is higher in lymphocytic leukemia." (PMID 35722492, 2022). "CAVIN1 and CAVIN2 are higher expressed in myeloid leukemias (including AML and CML) than that in lymphocytic leukemias (including ALL and CLL)." (PMID 35722492, 2022). "The results show that the transcription of CAVIN1, CAVIN2 and CAVIN3 were significantly lower than in normal samples from healthy donors, and the expression of CAVIN1 in myeloid leukemia is significantly higher than that in lymphocytic leukemia (p < 0.05)." (PMID 35722492, 2022).
oral squamous cell carcinoma (1 paper, 2022). "Cavin-2 downregulation in cancer tissues vs. control tissues has been reported in several malignant tumors, such as oral squamous cell carcinoma, and is associated with tumor progression." (PMID 35722492, 2022).
pulmonary fibrosis (1 paper, 2023). Chronic progressive interstitial lung disorder characterized by the replacement of the lung tissue by connective tissue, leading to progressive dyspnea, respiratory failure, or right heart failure. "Caveolin 1 has been found to prevent bleomycin-induced fibrosis by inhibiting inflammasome activation, although the roles of Cavin2 and Ehd2 in pulmonary fibrosis are not well-defined." (PMID 37852965, 2023).
renal carcinoma (1 paper, 2023). A carcinoma arising from the epithelium of the renal parenchyma or the renal pelvis. "On the contrary, 3 are linked with a favorable prognosis for renal cancer (SPTAN1, SPTBN1, CAVIN2)." (PMID 37775701, 2023).
cancer (15 papers, 2016 to 2025). A tumor composed of atypical neoplastic, often pleomorphic cells that invade other tissues. "Live cell imaging revealed increased colocalization of ATG9A-RFP and CAVIN2-GFP in cancer cells co-cultured with macrophages, a finding further supported by co-immunoprecipitation experiments." (PMID 40595560, 2025). "In the majority of human cancers, Cavin-1 is downregulated along with Cavin-2, Cavin-3 and Cavin-4 compared in cancer tissues vs. control tissues." (PMID 35722492, 2022). "Dysregulation of CAVIN2/SDPR has been reported to play vital roles in a variety of human cancers." (PMID 37497407, 2023). "CAVIN2 is also a tumor suppressor gene for NSCLC and its overexpression inhibits cancer proliferation." (PMID 36067196, 2022). "During the course of these experiments, we determined that A431 cells (similar to several other commonly cancer cell lines such as HeLa cells) do not express Cavin2 but have significant expression of the universal components of caveolae, Cavin1, CAV1, and Cavin3." (PMID 31332168, 2019).
tumor (11 papers, 2021 to 2025). "The loss of CAVIN2 expression disrupts membrane integrity and has been linked to increased cellular invasiveness, highlighting its function as a tumor suppressor." (PMID 40565055, 2025). "Cavin-2 is critical organizer of caveolae and plays a critical role in tumor cell proliferation, migration and invasion." (PMID 35722492, 2022). "Downregulation of CAVIN2 in tumor core vasculature was validated by immunostaining in human specimens." (PMID 34228647, 2021). "Here, we reported a novel tumor suppressor, serum deprivation-response protein (SDPR) (also called cavin-2), in inducing HCC cell apoptosis." (PMID 33931585, 2021). "At the same time, the expression of the antiapoptotic protein Bcl-xL was inhibited, and apoptosis was promoted, suggesting that Cavin-2 could be used as a tumor metastasis inhibitor." (PMID 37828916, 2023). "Furthermore, we demonstrated that CAVIN2/SDPR can function as a tumor suppressor in LUAD." (PMID 37497407, 2023). "Finally, experiments in vitro confirmed that CAVIN2/SDPR, functioned as a tumor suppressor, inhibited cell proliferation and migration in LUAD cells by inducing cell apoptosis and cell cycle arrest at S phase." (PMID 37497407, 2023).
infection (4 papers, 2023 to 2025). The state of being infected such as from the introduction of a foreign agent such as serum, vaccine, antigenic substance or organism. "Additionally, genes related to cell adhesion such as ADGRF5, CAVIN2, FAT3, FILIP1, GSN, and TSPAN11 were downregulated in both the variants at 24hpi whereas CAV1, CAVIN1, GPC3, POSTN, SUSD2, and TSPAN7 were downregulated only after Delta variant infection at 24 hpi." (PMID 41200555, 2025).
kidney disease (1 paper, 2017). "The repressive effect of H2O2, especially on caveolin-2/CAV2, PTRF/CAVIN1 and SDPR/CAVIN2 protein levels and the lack of effect on caveolin-1/CAV1 protein, argued against a major role of oxidative stress in induction of caveolar proteins in kidney disease." (PMID 29065889, 2017).
retinopathy (1 paper, 2017). "We noted a high level of Cavin-2 expression in the neovascular tufts in the mouse model of oxygen-induced retinopathy, suggesting a role for Cavin-2 in pathogenic angiogenesis." (PMID 28912276, 2017).
CAVIN2 also shares sentences with these, for which no sentence is quoted: hepatocellular carcinoma (3 papers); lung adenocarcinoma (2); acne (1); age-related macular degeneration (1); breast tumors (1); cardiac hypertrophy (1); diabetic nephropathy (1); endometrioid carcinoma of the ovary (1); gallstones (1); glaucoma (1); large cell lung carcinoma (1); liposarcoma (1); Luminal A (1); lymphoma (1); melanoma (1); myeloid leukemia (1); oral cancer (1); papillary thyroid cancer (1); prostate (1); psychiatric disorder (1); pulmonary hypertension (1); schistosomiasis (1); squamous cell lung carcinoma (1); stomach cancer (1).